MIR4445 (microRNA 4445)
Synonyms: hsa-mir-4445
Gene: MicroRNA gene on chromosome 3 (109,602,828 to 109,602,897, forward strand). Ensembl gene ENSG00000265956.
Homologues: Orthologues: chimpanzee MIR4445 (100% identical).